IL13 (interleukin 13)
Diseases named in the same sentence as IL13 in open-access papers (continued):
Sharing a sentence is not in itself a finding about the gene and the disease.
asthma (continued). "Monoclonal antibodies (mAbs) targeting specific cytokines, such as IL-5, IL-4/IL-13, and IgE, have provided significant benefits for patients with specific asthma phenotypes." (PMID 39902079, 2024). "In asthma, memory IgG-positive B cells class switches to IgE under the influence of IL-4 and IL-13 from T follicular helper cells, becoming long-lived plasma cells." (PMID 39518415, 2024). "Dupilumab, anti-IL-4R Ab, which suppresses the IL-4 and IL-13 signaling, is applicable for treating severe cases of asthma, chronic sinusitis with polyps, and atopic dermatitis." (PMID 39624446, 2024). "We compared this treatment effect to fluticasone, a mainstay treatment for asthma, and to soluble (s)IL-13Rα2, a treatment that neutralizes IL-13, a central mediator of type-2 inflammation." (PMID 39592603, 2024). "Mucous metaplasia can be triggered by inflammatory mechanisms and has been extensively studied in the context of Th2-dependent cytokines IL-4, IL-5, and IL-13, which play an important role within asthma." (PMID 39239645, 2024). "For instance, IL-13-induced epithelial cells exacerbate asthma inflammation by inducing monocyte proliferation and chemotaxis via exosomal signaling." (PMID 38655063, 2024). "About the Th2 cytokines IL-4/IL-13, some inhibitory monoclonal treatments contribute to decreasing asthma symptoms." (PMID 39840271, 2024). "The immune signature of asthma involves eosinophilia, IgE induction of airway smooth muscle, and increased levels of IL-4, IL-5, and IL-13." (PMID 39481080, 2024). "Th2 cells are mainly responsible for the allergic responses and asthma, as they secrete cytokines such as IL-4, IL-5, and IL-13." (PMID 39060348, 2024). "These particles also induce the release of IL-5 and IL-13, which play an important role in allergic airway diseases such as asthma, while stimulating type 2 ILCs to produce excess IL-5 and IL-13, leading to airway hyperresponsiveness." (PMID 38524119, 2024). "Dupilumab, a human anti-IL-4 receptor α monoclonal antibody that inhibits IL-4 and IL-13 signaling, decreases asthma exacerbations and mucus plugs and increases lung function in moderate to severe asthma." (PMID 38785953, 2024). "Out of these cytokines, IL-13 is a central mediator of allergic asthma and therefore one of the most important cytokines for asthma development and pathogenesis." (PMID 38732251, 2024). "IL-13, especially, has been identified as a critical mediator, influencing various cellular activities that lead to asthma's clinical manifestations." (PMID 38903705, 2024). "Mouse models of OVA-induced allergic airway inflammation show several characteristics of human asthma, including increased serum IgE concentrations, eosinophil infiltration, and increased levels of Th2 cytokines (IL-4, IL-5, and IL-13)." (PMID 39594470, 2024). "PAS staining also indicated an increase in mucus and mucus-producing goblet cells, which is consistent with the reported effects of IL-13 and type 2 inflammation in asthma and other airway diseases." (PMID 38706568, 2024). "The children with asthma had an inflammatory profile that was characterized by increased levels of several pro-inflammatory cytokines, including IL-2, IL-5, IL-13, IL-17A, IL-22, IL-33, TNF-α, and reduced level of anti-inflammatory cytokine, IL-10." (PMID 39902293, 2024). "The number of IL-5-, IL-10-, and IL-13-producing peripheral blood mononuclear cells (PBMCs) derived from all children at the asthma camp significantly (p < 0.05) decreased in the water aerosol group." (PMID 38398384, 2024). "Another recent study indicated that adults with obesity and asthma show slightly increased level of IL-17F and IL-13 compared to those with normal weight and asthma." (PMID 39902293, 2024). "Asthma induces bronchial inflammation, triggering the accumulation of inflammatory cytokines (such as IL-4, IL-5, and IL-13) and free radicals." (PMID 38931275, 2024).
asthma (continued). "Dupilumab, a human monoclonal antibody targeting the alpha subunit of the interleukin-4 receptor, effectively inhibits IL-4 and IL-13 signaling, which are crucial pathways in type 2 inflammatory diseases such as asthma." (PMID 39280557, 2024). "IL-13 contributes to goblet cell hyperplasia and mucus secretion during airway inflammation, which eventually increases airway resistance and lead to asthma exacerbations." (PMID 39717777, 2024). "Normal HBEC were differentiated in the presence of IL-13 for 14 days to induce a profibrotic phenotype similar to asthma." (PMID 38706568, 2024). "The pathogenesis of T2-high asthma is chiefly orchestrated by interleukins (IL)-4, IL-5, and IL-13 and is usually accompanied by eosinophil infiltration." (PMID 39685611, 2024). "Both IL-4 and IL-13 play inflammatory roles in the development of asthma and their expression is regulated." (PMID 39175819, 2024). "Dupilumab, an anti-IL-4Ra therapy, exhibits a higher remission rate, with about 30% of patients reaching remission, owing to its effective targeting of the IL-4/IL-13 pathway, crucial for type 2 inflammation-driven asthma." (PMID 39518449, 2024). "Since we are interested to understand the regulation of T2 inflammation in asthma, we studied if F2RL1 rs1529505 is associated with TH2 cells, TH2 cells’ ligand PGD2, cytokines IL-13 and CCL5, a T cell chemoattractant." (PMID 38308375, 2024). "A humanized monoclonal IL-13 neutralizing antibody called lebrikizumab was found to reduce asthma exacerbations and improve lung function in patients with moderate-to-severe asthma in a clinical trial." (PMID 39060923, 2024). "Activation of DCs and ILCs through alarmins (KE 2) plays key roles in driving type 2 inflammatory responses in asthma by promoting downstream production of type 2 cytokines such as IL-4, IL-5, and IL-13 from the effector cells (KE 3)." (PMID 39135743, 2024). "As a result, we propose the importance of carrying out site-specific glycosylation studies to determine the exact glycan compositional changes accompanying IL-13-induced asthma." (PMID 38732251, 2024). "Subsequently, we analyze the proteome and use the multi-omics results to characterize the chemical alterations upon IL-13 treatment, linking to asthma pathophysiology." (PMID 38732251, 2024). "Various studies have linked interleukin (IL) genes harbored in this gene cluster, particularly IL-13 and IL-4, to asthma pathogenesis." (PMID 38699097, 2024). "ILC2s reside on mucosal surfaces, including the lungs, and are capable of producing type 2 cytokines such as interleukin-5 (IL-5) and interleukin-13 (IL-13), which are pivotal in the pathogenesis of allergic disorders and asthma." (PMID 39346946, 2024). "Suppression of STAT3 prevents the production of IL‐4, IL‐13, and IL‐17, which are upregulated in asthma." (PMID 38286741, 2024). "Hypoxia can influence CD8+ type 2 cytotoxic T cells via HIF‐α, leading to increased IL‐13 secretion and worsening asthma." (PMID 38629734, 2024). "BAs such as anti-IgE, anti-IL5, and anti-IL-4/IL-13 monoclonal antibodies (mAb) were found to be effective in the CRSwNP treatment of patients with severe asthma, with the most significant reduction being observed in the anti-IL-4R-mAb-receiving group." (PMID 38541174, 2024). "There are several biological drugs currently available to treat severe asthma: anti-IL-5 (mepolizumab, reslizumab, benralizumab), anti-IgE (omalizumab), anti-IL-4/IL-13 (dupilumab), and anti-TSLP (tezepelumab) agents." (PMID 39685611, 2024). "The study found that this combination significantly reduced the presence of Th2/Th17-derived cytokines (IL-4, IL-5, IL-13, IL-17A), immunoglobulin E, and leukotriene C4 in bronchoalveolar lavage fluid and serum, key contributors to allergies and asthma." (PMID 39857357, 2024). "Here, authors reveal a role for intelectin-1 in IL-13-induced mucus properties, and that an ITLN1 eQTL is associated with protection from the formation of mucus plugs in T2-high asthma." (PMID 38724552, 2024).
asthma (continued). "IL-13 contributes to various asthma symptoms, such as airway hyperresponsiveness, mucus production, IgE synthesis, and the activation of eosinophils and mast cells." (PMID 39421735, 2024). "It has been shown that IL-13 disrupts bronchial epithelial integrity by affecting tight junctions in individuals with asthma." (PMID 38680486, 2024). "The most common inflammatory endotype is type 2 (T2)-high asthma, characterised by high levels of T2 inflammatory biomarkers including eosinophils, exhaled nitric oxide, IgE, interleukin (IL)-5 and IL-13." (PMID 38609094, 2024). "Th2 cells are crucial in the pathogenesis of asthma due to their secretion of IL-5 and IL-13, which promote eosinophilic inflammation and BHR." (PMID 39459021, 2024). "Taken together, these data support a mechanism of pathologic mucus formation in asthma in which airway epithelial cells activated by IL-13 can autonomously generate pathologic mucus via peroxidase-mediated cross-linking of mucin polymers." (PMID 38889046, 2024). "RT-qPCR results showed that SNHG9, AC007952.4 and ACER3 were significantly decreased in the IL-13-induced asthma cellular model than in the control group, while hsa-miR-125a-5p, hsa-miR-615-3p showed high expression (P < 0.05)." (PMID 38297226, 2024). "Lastly, the ceRNA network was confirmed by qRT-PCR and RNAi experiments in the characteristic cytokine (IL-13)-induced asthma cellular model." (PMID 38297226, 2024). "IL-13 is a pivotal cytokine in the initiation and advancement of asthma, particularly in allergic asthma." (PMID 39407835, 2024). "Given that Th2 cells secrete IL-5 and IL-13 during asthma exacerbation, we further examined the effect of CBD-X extract on the secretion of these cytokines." (PMID 39459021, 2024). "Th2 cells, which predominate in allergic reactions and asthma, are the primary source of the type 2 cytokines IL-4, IL-5, and IL-13." (PMID 38731707, 2024). "It is well known that Th1/Th2 immune dysregulation is a common feature of asthmatic airway inflammation and that cytokines IL-4, IL-5, IL-6 and IL-13 produced by Th2 cells play an important role in asthma pathogenesis." (PMID 38579176, 2024). "IL5 and IL13 are major cytokines involved in asthma pathogenesis, related to differentiation, production, maturation, and activation of eosinophils, activation of fibroblasts, increased mucus production, and airway hyperresponsiveness." (PMID 38655128, 2024). "Other markers previously associated with type 2 inflammation in asthma, including CLCA1, SERPINB2, and SPDEF, were significantly (p < 0.0001) increased in the IL-13 treated HBEC compared to normal HBEC." (PMID 38706568, 2024). "A phase I study by Burgess and colleagues investigating the safety of a dry powder formulation of anti-interleukin-13 monoclonal antibody fragment for asthma resulted in one subject testing positive for treatment-associated immunogenicity." (PMID 39202058, 2024). "Further studies on animal models provided supporting evidence that SLC26A4 is indeed expressed in the lungs of asthma model mice, including those induced by ovalbumin inhalation, IL-13 inhalation, and IL-13 transgenic mice." (PMID 39100210, 2024). "In type 2-high asthma, B cells produce IgE under the influence of the Th2 cytokines, IL-4 and IL-13." (PMID 36845128, 2023). "Note that the frequency of IL5+ and IL13+ CD4 T cells was low in control wild type mice in our asthma model." (PMID 37575259, 2023). "Increasing the abundance of these genera can improve microbial dysbiosis, regulate the diversity of intestinal microbiota, reduce the levels of inflammatory factors, namely, IL-4, IL-5, and IL-13, and alleviate the development of asthma airway inflammation." (PMID 36636604, 2023). "IL-4, IL-5, and IL-13 are responsible for many of the common cellular responses to asthma, including inflammatory cell infiltration, mediator release, and airway remodeling." (PMID 37892224, 2023).
asthma (continued). "Interleukin (IL)-4, IL-5 and IL-13, plays a vital role in the pathophysiology of eosinophilicairway diseases such as asthma, chronic rhinosinusitis, eosinophilic granulomatosis with polyangiitis and hypereosinophilic syndrome." (PMID 37886149, 2023). "On the other side, dysregulated IL-13 signaling in the airways of asthmatics contributes to the epithelial barrier dysfunction observed in asthma." (PMID 37629063, 2023). "For example, a previous study showed that abnormality CDH26 gene are characterized by IL-13 stimulation of the airway epithelium and T2 inflammation of the airway epithelium in asthma development." (PMID 37438356, 2023). "This study opens up new ways to study the potential regulatory function of hY3 over IL-13 production and its implications for asthma development." (PMID 36089628, 2023). "Unlike corticosteroids which target an unspecified range of cells, biological therapies specifically target inflammatory cytokines (IL-4, IL-5, and IL-13), of T2-high asthma." (PMID 38259298, 2023). "There were significant differences in the distribution of the three genotype frequencies which including the gene loci ADRB2 rs1042713, IL4 rs2243250 and IL13 rs20541 between the asthma group and the control group." (PMID 38049812, 2023). "Kuperman found increased pendrin expression in three mouse asthma models, along with marked IL-13 upregulation." (PMID 36983684, 2023). "It is known that TNF-α, IL-4, and IL-13 release is triggered by IL-33 and drives the type 2 inflammatory pattern seen in asthma." (PMID 37153601, 2023). "Interleukin-13 (IL-13) is a cytokine involved in T-cell immune responses and is a well validated therapeutic target for the treatment of asthma, along with other allergic and inflammatory diseases." (PMID 37483614, 2023). "Abnormal T-helper type 2 (Th2) inflammation is the most important pathological process in asthma, mediated by Th2 cytokines such as interleukin (IL)-5, IL-4, and IL-13." (PMID 37174726, 2023). "Lower doses of Suhuang can inhibit airway inflammation and remodeling in OVA-induced asthma by inhibiting IL-13 and TGF-β1." (PMID 38074219, 2023). "Another IgG4 neutralizing IL-13 mAb, Tralokinumab, has also been tested in large clinical trials in severe asthma patients." (PMID 37163370, 2023). "Whereas total Tc/Th cell frequencies were similar between asthma patients and HCs, production of the type-2 cytokines IL-5, IL-9, and IL-13 by both Tc and Th cells was significantly higher in asthma patients than in HCs." (PMID 37612281, 2023). "Once stimulated, ILC2 and Th2 produce type 2 cytokines, including IL-4, IL-5, and IL-13, responsible for the main alterations present in asthma." (PMID 37947596, 2023). "Studies demonstrate that controlling Th2-type asthma is effective via the preparation of anti-IL-4/IL-13 antibodies." (PMID 37873538, 2023). "Dupilumab is the first fully human anti-IL-4 receptor α monoclonal antibody approved for asthma that blocks both IL-4 and IL-13 signaling." (PMID 37377958, 2023). "By blocking the shared receptor component for IL-4 and IL-13, dupilumab improves upper and lower airway outcome measures in patients with severe CRSwNP and comorbid asthma, as reported by the body of evidence." (PMID 37464395, 2023). "Cytokines such as IL-4, IL-5, IL-9 and IL-13 and their receptors have been chosen as targets for monoclonal antibody-based treatments due to their importance in the pathogenesis of asthma." (PMID 37334374, 2023). "To determine the effects of IL-31 on the expression of asthma-associated genes, we quantified the expression of genes associated with inflammation (IFNγ, TNF-α, IL-6, and IL-17) and Th2 responses (IL-4, IL-13, ARG1, MUC4, and MUC5AC)." (PMID 38081868, 2023). "Dupilumab, the first fully human anti-IL-4 receptor mAb, approved in 2018 for add-on maintenance treatment of severe asthma, blocks both IL-4 and IL-13 from binding to IL-4Rα." (PMID 38203353, 2023).
asthma (continued). "Although IL-13 being a cytokine involved in asthma, we found high levels of either in the induced emphysema groups (ELA and ACO)." (PMID 37511021, 2023). "IL-13 and IL-5 secretion by PBMCs from patients with asthma were also negatively correlated with the plasma levels of α-MSH." (PMID 37699899, 2023). "Interleukin-13 (IL-13), secreted by Th2 cells, is related to airway inflammation and allergy in asthma." (PMID 37896834, 2023). "Since serum periostin was found to be relatively unsuccessful in identifying an asthma population that particularly benefit from anti-IL-13 treatment, interest in periostin as a phenotype-specific biomarker has been somewhat reduced." (PMID 36763690, 2023). "Th2 cells, which produce IL-4, IL-5, and IL-13 in an antigen-dependent manner, are thought to play a major role in the pathogenesis of asthma." (PMID 37377958, 2023). "The Th2 cytokines, interleukin-4 (IL-4) and interleukin-13 (IL-13), are well recognised for their roles in allergic diseases, such as asthma." (PMID 37949903, 2023). "In a mouse model of asthma, an increased expression of miR-21 and repression of miR-1 in IL-13 transgenic mice have been reported, in which there is an over-expression of IL-13 in a lung-specific manner." (PMID 37374157, 2023). "For example, anti-asthma monoclonal antibodies against pro-allergic immunoglobulin E (IgE), IL-5, IL-4, and IL-13 have been developed." (PMID 36865540, 2023). "Our in vivo experiments further confirmed that autophagy was activated in OVA-induced asthma models, and the application of autophagy inhibitor CQ significantly reversed Th2 cytokines release (IL-5/IL-13), airway resistance and remodeling." (PMID 37674165, 2023). "Based on accumulating evidence implicating IL-4, IL-5, and IL-13 are responsible for the occurrence and development of asthma." (PMID 37377958, 2023). "For a long time, inflammatory diseases were thought to associate with either an IFNγ-driven Th1-type inflammatory response (e.g. multiple sclerosis) or a Th2-type response characterised by the expression of IL-4, IL-5 and IL-13 (e.g. asthma)." (PMID 35275333, 2023). "IL-13 mediates allergic responses in patients with asthma and induces bronchial hyperresponsiveness, goblet cell hyperplasia, and mucin production." (PMID 37511021, 2023). "In type 2-low asthma, the upregulation of T2 immune pathways (e.g., IL-4 and IL-13) and eosinophilic inflammation characteristic of type 2-high phenotype are classically absent, contributing to the poor response to corticosteroids." (PMID 37108417, 2023). "Radhakrishnan A.K., Raj V.L., Tan L.K., Liam C.K. Single nucleotidepolymorphism in the promoter of the human interleukin-13 gene isassociated with asthma in Malaysian adults." (PMID 37465198, 2023). "As sputum cytokines were not investigated as part of the BIOAIR study, we carried out an additional investigation into the relationship between sputum periostin with sputum IL-4 and IL-13 in a separate cohort of patients with asthma." (PMID 36763690, 2023). "RELMβ is strongly produced in the lungs of mice with experimental asthma caused by multiple allergens (OVA and Aspergillus) and Th2 cytokines (IL-4 and IL-13) via IL-13- and STAT6-dependent mechanisms." (PMID 36691020, 2023). "Our study revealed IL-13 as one of the most important targets for asthma with approved drugs on the market currently." (PMID 37735578, 2023). "JAK inhibitors are an attractive small molecule option given the widespread signaling of cytokines and growth factors using JAK-STAT receptors in asthma, including IL-4, IL-5, IL-13, GM-CSF, IFN-α, IFN-β, IFN-γ, and TSLP." (PMID 37265457, 2023). "Patients with high serum levels of periostin had a greater improvement in lung function and reduced asthma exacerbations following treatment with the anti–IL-13 lebrikizumab." (PMID 37035303, 2023).